ABCG5 (ATP binding cassette subfamily G member 5)
Diseases named in the same sentence as ABCG5 in open-access papers (continued):
Sharing a sentence is not in itself a finding about the gene and the disease.
Hepatic steatosis (5 papers, 2017 to 2023). Steatosis is a term used to denote lipid accumulation within hepatocytes. "Several human and animal studies have linked ABCG5/G8 variants and expression with cardiometabolic traits, such as insulin sensitivity, glycemic control, blood pressure status, and fatty liver disease." (PMID 36981027, 2023). "For example, mice deficient in ABCG5 and ABCG8 are prone to the development of fatty liver disease and liver injury." (PMID 30679232, 2019). "Animal studies also showed that mice with ABCG5/G8 deficiencies may cause hypertriglyceridemia via multiple metabolic pathways and that sterol transportation via ABCG5 and ABCG8 opposes the development of fatty liver disease and loss of glycemic control independently of phytosterol accumulation." (PMID 36981027, 2023). "Thus, FGF19 and NGM282 appear to selectively modulate LXR signaling, upregulating canonical LXR target genes (Abcg5, Abcg8, Scarb1, Srebf1, Fasn, Scd1, Srebf2, and Scap) without inducing hepatic steatosis." (PMID 30679232, 2019). "In addition, NCEH1, ABCG5, and ABCG8 are reported to be drug targets of pioglitazone and ezetimibe in the therapy of human gallbladder cholesterolosis and HFD-induced fatty liver." (PMID 29464180, 2017).
lipid metabolic disorder (5 papers, 2020 to 2026). "The aim of this work was to study the spectrum of rare variants in the cholesterol transporter genes ABCA1, ABCG1, ABCG5, ABCG8 and NPC1L1 that occur in patients with lipid metabolism disorders in the population of the Northwestern region of Russia." (PMID 42253452, 2026). "The search for rare variants (gnomAD frequency less than 1 %) in the ABCA1, ABCG1, ABCG5, ABCG8 and NPC1L1 genes was performed using targeted sequencing data for 169 patients with lipid metabolism disorders." (PMID 42253452, 2026). "This review focuses on the regulation of lipid metabolism disorders by the gut microbiota through the effects of bile acids (BA), short-chain fatty acids (SCFAs), bile salt hydrolase (BSH), and genes such as ABCG5 and ABCG8, FXR, NPC1L, and LDL-R." (PMID 33005189, 2020).
coronary artery disease (4 papers, 2021 to 2025). "Recently, it has also been reported that heterozygous carriers of ABCG5 variants had a 2-fold increase in the risk of coronary artery disease." (PMID 34880906, 2021). "Previous studies have suggested that heterozygous carriers of loss-of-function ABCG5 variants exhibit elevated levels of sitosterol and LDL-C, which may increase their risk of coronary artery disease." (PMID 39860331, 2025).
Hypertension (4 papers, 2005 to 2022). The presence of chronic increased pressure in the systemic arterial system. "The Spontaneous hypertensive rat (SHR) harbors a glycine 583 cysteine mutation in Abcg5, which segregates with elevated phytosterol levels in plasma, but not hypertension." (PMID 33807969, 2021).
hypertriglyceridemia (4 papers, 2019 to 2023). A laboratory test result indicating elevated triglyceride concentration in the blood. "In the present study, in a prediabetic HHTg model with severe hypertriglyceridemia we observed markedly increased expression of Abcb1b, Abca1, and Abcg8 genes and decreased expression of Abcb1a and Abcg5 genes." (PMID 37077818, 2023). "Acceleration of ABCG5/G8-mediated biliary cholesterol secretion showed restoration of glycemic control and alleviation of hypertriglyceridemia in obese db/db mice." (PMID 36981027, 2023).
Cholecystitis (3 papers, 2022 to 2025). The presence of inflammatory changes in the gallbladder. "Previous studies have shown that patients with cholesterol stone disease and cholecystitis have increased levels of ABCG5 expression." (PMID 40428345, 2025).
Macrothrombocytopenia (3 papers, 2021 to 2025). "In the course of the evaluation, ABCG5 heterozygosity was identified as a cause of autosomal dominant inherited macrothrombocytopenia; the role of ABCG5 in macrothrombocytopenia and its therapy with Ezetimibe should be further investigated." (PMID 34880906, 2021). "In particular, one heterozygous rat (G5G8+ +/- -) also had this biased distribution of platelet size, similar to the maternal kindred with Var2, suggesting that heterozygotes of this ABCG5 variant might be sufficient to cause macrothrombocytopenia." (PMID 34880906, 2021).
melanoma (3 papers, 2013 to 2025). A malignant, usually aggressive tumor composed of atypical, neoplastic melanocytes. "The ABCG5+ cells represent 2–20 % of the melanoma tumours and have been shown to successfully recapitulate the tumour in immuno-deficient mice; however, these tumours were unable to regenerate ABCG5+ cells, suggesting their limited stemness capacity." (PMID 27825361, 2016).
colitis (2 papers, 2021 to 2023). Inflammation of the colon. "However, interestingly, the expression of genes involved in cholesterol excretion such as ABCG5, and ABCG8 was not changed, while the expression of BSEP, a major bile acid transporter, was significantly decreased in the liver of FMT-colitis mice compared to that of FMT-control group." (PMID 36735734, 2023).
colorectal cancer (2 papers, 2012 to 2025). A primary or metastatic malignant neoplasm that affects the colon or rectum. "The same can be said about ABCG5, which is a poor predictor of colorectal cancer and is linked to increased xenobiotic resistance in head and neck cancers." (PMID 39861164, 2025). "In a previous immunohistochemical study on colorectal cancer from the several potential CSC markers (ABCG5, ALDH1, CD24, CD44, CD90, CD133, EpCam) that have been proposed for solid tumors, only ABCG5 expression in tumor budding cell was found to be associated with poor survival of the patients." (PMID 23316479, 2012).
coronary atherosclerosis (2 papers, 2019 to 2023). Atherosclerosis of the coronary vasculature. "Elevation of sitosterol serum concentrations due to ABCG5/G8 mutations also showed risk-increasing causal relationships with a detrimental effect on coronary atherosclerosis." (PMID 36981027, 2023).
hepatoma (2 papers, 2018). "Furthermore, in vitro experiments in primary mouse hepatocytes and human hepatoma cell lines HuH7 and HepG2 together with in vivo experiments demonstrated that IL-1β exposure was sufficient to suppress transcription of Nr1h4, Abcb11, Abcc2, and Abcg5/8, findings that characterize the PNAC liver." (PMID 29643332, 2018).
liver disease (2 papers, 2020 to 2025). "As shown in the heat map, male offspring exposed to HSD exhibited differential expression of ten genes associated with liver disease compared to normal offspring: Ager, Dph1, Steap4, Nfe2l1, Ppara, Rbmx, Nr1d1, Ccar2, Axl, and Abcg5." (PMID 41036197, 2025).
Sepsis (2 papers, 2012 to 2021). Sepsis is defined as life-threatening organ dysfunction caused by a dysregulated host response to infection. "Sepsis was also associated with decreased mRNA abundance of hepatic Abcg5/g8 expression (the canalicular cholesterol transporter) and down regulation of the bile acid transporter Abcb11." (PMID 23145105, 2012). "Similarly, hepatic expression of transporters involved in export of cholesterol to bile and gut (Abcg5 and Abcg8) was unaffected by sepsis or 3HB supplementation." (PMID 34274000, 2021).
acute pancreatitis (1 paper, 2024). An acute inflammatory process that leads to necrosis of the pancreatic parenchyma. "We also confirmed the findings of variants around ABCG5 gene associated with acute pancreatitis by a recent GWAS meta-analysis which including the UK Biobank30." (PMID 38491158, 2024). "The GWAS from UK Biobank alone identified 3 variants associated with acute pancreatitis and the top signal was a variant in the intron of the ABCG5." (PMID 38491158, 2024).
intrahepatic cholestasis (1 paper, 2017). A cholestasis characterized by impairment of the bile flow caused by obstruction located in the liver. "The reduced expression of the canalicular transporters ABCC2, ABCG2 and of the cholesterol transporter ABCG5 leads to impaired bile acid, bilirubin and cholesterol excretion and in the long term to intrahepatic cholestasis as was observed in DILI patients treated with diclofenac." (PMID 29296203, 2017).
liver cancer (1 paper, 2024). An epithelial or non-epithelial malignant neoplasm that arises from the liver. "To corroborate the data, we also evaluate the expression of NR1H3, ABCG5 and ABCG8 in four different GEO datasets of human liver cancer, observing a significant reduction of their level in tumour tissue compared to non-tumoral one." (PMID 38824560, 2024).
lysosomal acid lipase deficiency (1 paper, 2025). "No homozygous variants were detected in the recessive genes, i.e. no autosomal recessive hypercholesterolemia (LDLRAP1), siterolemia (ABCG5/8) or lysosomal acid lipase deficiency (LIPA)." (PMID 39802654, 2025).
migraines (1 paper, 2023). "In contrast, ABCG5/ABCG8 enhancement, APOB inhibition, NPC1L1 inhibition, PCSK9 inhibition was found to be suggestively associated with higher risk of migraine." (PMID 37596566, 2023). "Our findings suggested the possibility, without confirmation, that exposure to bile acid sequestrants targeting ABCG5/ABCG8, cholesterol absorption inhibitors targeting NPC1L1, and Mipomersen targeting APOB might increase the likelihood of migraines in individuals." (PMID 37596566, 2023).
primary biliary cirrhosis (1 paper, 2019). "In addition, seladelpar, a selective PPARβ/δ agonist, modulated the reversed cholesterol transporter ABCG5/ABCG8 during primary biliary cirrhosis treatment." (PMID 31336903, 2019).
prostate carcinoma (1 paper, 2020). A carcinoma that arises from epithelial cells of the prostate gland. "ABCG5 methylation was inversely correlated with ABCG5 expression, suggesting that DNA methylation might contribute to the differential aggressiveness of prostate cancer in African-American and Caucasian patients." (PMID 33066132, 2020).
psoriasis (1 paper, 2023). An autoimmune condition characterized by red, well-delineated plaques with silvery scales that are usually on the extensor surfaces and scalp. "Given a bile acid imbalance has been observed in patients with psoriasis and psoriatic arthritis and the role of ABCG5/8 in the TICE, we speculate whether ABCG5 and ABCG8 play a role in the bile acid metabolism of psoriasis." (PMID 37234169, 2023).
sitosterolemia 1 (1 paper, 2022). "In contrast, Sitosterolemia 1 caused by ABCG5 is more prevalent in Indians, Chinese, and Japanese." (PMID 36329474, 2022).
steatosis (1 paper, 2018). Increased lipid within the cytoplasm of cells. "Interestingly, liver protein expression of ABCG8 and ABCG5 has been suggested to be higher and expression of NPC1L1 to be lower in those with steatosis and NASH compared to those with normal liver." (PMID 29540533, 2018). "ABCG5/8 protein expression was reported to be higher in those with steatosis compared to those with normal liver, a finding not confirmed in our study." (PMID 29540533, 2018).
tumor (14 papers, 2010 to 2025). "Moreover, according to the same study, unlike CD166, CD133, CD24, CD90, CD44s and ALDH1, the expression of EpCAM and ABCG5 within tumor buds is often associated with a poor prognosis." (PMID 40564019, 2025). "Our previous studies have identified ABCA6, ABCC6 and ABCG5 as potential tumor-suppressor genes in HCC." (PMID 35280774, 2022). "Since vitamin K3 functions as an anti-tumor agent and cisplatin—an anticancer drug—resistant cells were also resistant to vitamin K3 treatment, ABCG5/ABCG8 may play a role in resistance of cancer cells to vitamin K3 cytotoxicity." (PMID 36839356, 2023). "Furthermore, we measured the expression of ABCA6, ABCC6, and ABCG5 in 50 pairs of early-stage tumor tissues and paratumor tissues using quantitative reverse transcription polymerase chain reaction (qRT-PCR)." (PMID 35280774, 2022). "Recently, some studies indicated that CRC tumor budding cells had high expression of markers of cancer stem cells, such as CD44, CD133 and ABCG5, and suggested that some tumor budding cells in CRC might contain subgroups of cancer stem cells." (PMID 30046385, 2018). "Intriguingly, in tumour tissue of WD-fed mice, while the expression of Nr1h3 was significantly induced, the mRNA levels of its target genes involved in cholesterol excretion Abcg5/8 and de novo lipogenesis (Srebp1c, Fasn, Scd1) were not changed between the two groups of mice." (PMID 38824560, 2024). "Interestingly, ABCG5-expressing and non-expressing buds have differential effects on patient survival supporting the notion that the level of aggressiveness of tumor buds may depend on their protein profiles." (PMID 21317460, 2010). "ABCG5 positivity in tumor buds have been proposed as an indicator of poor prognosis in node-negative CRC patients, whereas in TCGA tumors, ABCG5 seems to have a favorable effect in liver prognosis." (PMID 33194695, 2020). "Low expression of FITM1, ABCG5, BSCL2, and GPAM in non-viral HCC tumor specimens generally predicted worse survival status." (PMID 32174969, 2020).
genetic disorder (6 papers, 2014 to 2026). "Hyperphytosterolemia, a rare genetic disorder caused by inactivating mutations in the ABCG5/8 genes, is associated with an increased risk of cardiovascular disease." (PMID 40661798, 2025).
cardiovascular disease (5 papers, 2009 to 2025). "One variant, ABCG5: c.1593C>A (p.Asn531Lys), was reported by Ambry Genetics in an individual with cardiovascular disease." (PMID 39860331, 2025). "The link between GSD and cardiovascular disease is thought to arise through ABCG5/8, a transporter protein that promotes the secretion of cholesterol and phytosterols into the bile." (PMID 37914780, 2023).
ABCG5 also shares sentences with these, for which no sentence is quoted: cancer (5 papers); choledocholithiasis (2); gallbladder cholesterolosis (2); inflammation (2); Arrhythmia (1); Arthritis (1); B-Cell CLL (1); bladder (1); breast carcinoma (1); cardiomyopathy (1); carnitine deficiency (1); central obesity (1); Crigler-Najjar syndrome (1); dengue fever (1); Dubin-Johnson syndrome (1); E. coli infection (1); endotoxemia (1); familial chylomicronemia syndrome (1); gallbladder cancer (1); head and neck cancer (1); Hyperglycemia (1); infection (1); inflammatory bowel disease (1); lung adenocarcinoma (1); lymphoma (1); metabolic disorders (1); myocardial infarction (1); neurological disease (1); non-alcoholic fatty liver disease (1); palmoplantar keratosis (1).
A further 6 diseases each share a sentence with ABCG5 in 1 paper.